MARS1 (methionyl-tRNA synthetase 1)
Description:
Catalyzes the specific attachment of L-methionine to its cognate tRNA in a 2 step reaction: the amino acid (AA) is first activated by ATP to form AA-AMP and then transferred to the acceptor end of the tRNA. Plays a role in the synthesis of ribosomal RNA in the nucleolus. In addition, can prevent the misincorporation of homocysteine into tRNA and protein by catalyzing a tRNA-independent hydrolysis of the misactivated homocysteinyl-AMP intermediate. The homocysteinyl-AMP intermediate undergoes an intramolecular cyclization reaction in which the thiolate side chain of homocysteine displaces the AMP group, forming homocysteine-thiolactone and AMP (By similarity).
Synonyms: MetRS; MARS; SPG70; CMT2U; ILFS2; ILLD; MRS; MTRNS; TTD9
Tractability: Small molecule: a structure with a bound ligand is known; it belongs to a druggable protein family. PROTAC: ubiquitination databases record sites on it; a small molecule that binds it is known.
Target class: Enzyme; Ligase
Gene: Protein-coding gene on chromosome 12 (57,475,445 to 57,517,569, forward strand). Ensembl gene ENSG00000166986.
Subcellular location: Cytoplasm, cytosol; Nucleus, nucleolus
Subcellular location (Human Protein Atlas): Cytosol; End piece; Mid piece; Principal piece
Pathways (Reactome):
Developmental Biology: Transcriptional and post-translational regulation of MITF-M expression and activity
Metabolism: Selenoamino acid metabolism
Metabolism of proteins: Cytosolic tRNA aminoacylation
Gene Ontology:
Molecular function: methionine-tRNA ligase activity; aminoacyl-tRNA ligase activity; ATP binding; nucleotide binding
Biological process: cellular response to epidermal growth factor stimulus; cellular response to platelet-derived growth factor stimulus; homocysteine metabolic process; methionyl-tRNA aminoacylation; positive regulation of transcription of nucleolar large rRNA by RNA polymerase I; rRNA transcription; tRNA aminoacylation for protein translation
Cellular component: aminoacyl-tRNA synthetase multienzyme complex; cytoplasm; cytosol; extracellular exosome; membrane; nucleolus
Genetic constraint (gnomAD): Loss-of-function variants: 80 observed, 124.01 expected, observed/expected ratio (o/e) 0.65, 90% interval 0.54 to 0.78. The upper end of that interval is the gene's LOEUF score, 0.78, which puts it in group 3 of 6, group 1 being the genes least tolerant of losing a copy. Missense variants: 945 observed, 1,175.9 expected, observed/expected ratio (o/e) 0.8, 90% interval 0.76 to 0.85. Synonymous variants: 418 observed, 460.02 expected, observed/expected ratio (o/e) 0.91, 90% interval 0.84 to 0.99.
Gene-disease validity (ClinGen):
ClinGen rates the evidence that MARS1 causes each of these diseases.
Charcot-Marie-Tooth disease (autosomal dominant): Limited. An inherited degenerative disorder involving the peripheral nerves.
Homologues: Orthologues: chimpanzee MARS1 (99% identical), macaque MARS1 (98% identical), dog MARS1 (94% identical), pig MARS1 (94% identical), rabbit MARS1 (93% identical), guinea pig MARS1 (91% identical), rat Mars1 (91% identical), mouse Mars1 (90% identical), tropical clawed frog mars1 (67% identical), zebrafish mars1 (64% identical), Drosophila melanogaster MetRS (49% identical), Caenorhabditis elegans mars-1 (39% identical). Paralogues in human: VARS1 (19% identical), MARS2 (16% identical), VARS2 (15% identical), IARS1 (13% identical), IARS2 (13% identical), LARS1 (12% identical), LARS2 (12% identical).
Diseases named in the same sentence as MARS1 in open-access papers:
MARS1 is named in the same sentence as 41 diseases in open-access papers, as found by Europe PMC text mining. Sharing a sentence is not in itself a finding about the gene and the disease. The quoted sentences say what the papers report.
Sepsis (11 papers, 2019 to 2025). Sepsis is defined as life-threatening organ dysfunction caused by a dysregulated host response to infection. "In a similar approach, Scicluna and coworkers generated genome-wide blood gene expression profiles and characterized four molecular endotypes of sepsis, one of which (MARS-1) was found to be consistently associated with the worst outcomes." (PMID 30994733, 2019). "Besides, our research also showed that most sepsis patients with high risk might have the Mars1 endotype which indicated the poor prognosis of patients with the Mars1 endotype." (PMID 36532037, 2022). "In the recent past, patients with sepsis have been divided into several subtypes based on blood RNA expression profiles, including Mars1 to Mars4, subtypes named “inflammopathic, “adaptive” and “coagulopathic”, and SRS1 and SRS2." (PMID 38504349, 2024). "Our group reported four sepsis transcriptome endotypes, named Mars1 to Mars4, in patients with sepsis." (PMID 36470832, 2022). "Through machine learning and analysis of DEGs, sepsis was classified into four subtypes, MARS1-4." (PMID 41285832, 2025). "Finally, the Molecular Diagnosis and Risk Stratification of Sepsis (MARS) consortium utilized genome-wide blood gene expression profiles to group patients into endotypes MARS1-4 for adult patients and MARS1, 2, and 4 for pediatric patients." (PMID 39469706, 2024). "Two studies have identified two gene expression signatures associated with immunoparalysis in severe CAP, similar to those found in the present work: sepsis response signature 1 (SRS1) and molecular diagnosis and risk stratification of sepsis 1 (MARS1), which predict fatal outcome." (PMID 31500177, 2019).
liver disease (5 papers, 2018 to 2023). "Rare inherited metabolic diseases such as mutations affecting the MARS1 gene encoding methionine tRNA synthetase (MetRS) can cause severe lung and liver disease before the age of two years." (PMID 36986818, 2023). "LARS1- and MARS1-associated disorders are associated with neurological impairment, MRI abnormalities, liver disease, anemia, and endocrine abnormalities and show the greatest clinical overlap with the YARS1 p.(Arg367Trp)-associated phenotype delineated here." (PMID 34536092, 2021). "Thus, it can be concluded that nicotinamide may affect liver inflammation by regulating the gene expression of MARS1, CDH11 and their related signal pathways, thereby preventing the occurrence of liver diseases." (PMID 37233635, 2023).
lung carcinoma (4 papers, 2020 to 2025). "Combining MARS1 staining with conventional cytology also improves the accuracy of diagnosis in patients with suspected lung cancer." (PMID 40722532, 2025). "Dual IF staining using combinations of MARS1, ARS-interacting multifunctional protein-lacking exon 2 (AIMP2-DX2), and/or pan-cytokeratin is also an effective diagnostic tool, which can improve lung cancer diagnostic yield by complementing conventional cytology." (PMID 40722532, 2025).
non-small cell lung carcinoma (3 papers, 2017 to 2025). A group of at least three distinct histological types of lung cancer, including non-small cell squamous cell carcinoma, adenocarcinoma, and large cell carcinoma. "Dual MARS1/CD45 IF staining has good diagnostic performance and may be a valuable addition to cytology tests in determining lymph node metastasis of non-small-cell lung cancer (NSCLC)." (PMID 40722532, 2025).
breast carcinoma (2 papers, 2025). "Similarly, elevated levels of MARS1 expression in breast cancer tissue have been linked to reduced survival, indicating its potential as both a diagnostic and prognostic biomarker in that context." (PMID 40722532, 2025). "Depletion of PUS1 and MARS1 has been shown to suppress cancerous phenotypes in hepatocellular carcinoma, renal cell carcinoma, and breast cancer." (PMID 40918643, 2025).
Charcot-Marie-Tooth (CMT) disease (2 papers, 2023). "Thus far, autosomal dominant mutations in AARS1, GARS1, HARS1, MARS1, WARS1, SARS1 and YARS1 have been linked to peripheral neuropathies, predominantly Charcot-Marie-Tooth (CMT) disease." (PMID 37274211, 2023).
neuropathy (2 papers, 2015 to 2023). A disorder affecting the nervous system that manifests with pain, tingling, numbness, and/or muscle weakness. "The MARS1 variants that have so far been linked to neuropathy occur in highly conserved residues of the protein." (PMID 37274211, 2023).
Pancreatic Cancer (2 papers, 2023 to 2025). "In this study, we investigated the diagnostic utility of methionyl-tRNA synthetase 1 (MARS1) through immunohistochemical (IHC) and immunofluorescence (IF) staining as a potential biomarker for pancreatic cancer." (PMID 40722532, 2025). "On MARS1 IF staining, pancreatic cancers were defined by the presence of a strong green signal in the cytosol of cells, and benign specimens were defined by the presence of a dim green signal or no signal." (PMID 40722532, 2025). "In the present study, MARS1 IF staining was more sensitive than conventional Pap staining (97.4 vs. 73.2%) in diagnosing pancreatic cancer." (PMID 40722532, 2025). "The sensitivity for detecting pancreatic cancer was significantly higher for MARS1 IF staining than for conventional Pap staining (97.4% vs. 79.1%, p < 0.0001)." (PMID 40722532, 2025). "We found that MARS1 expression was clearly higher in pancreatic cancer than in normal pancreatic ductal tissues." (PMID 40722532, 2025). "MARS1 IF staining distinguished pancreatic cancer in specimens with atypia on Pap staining." (PMID 40722532, 2025).
pulmonary alveolar proteinosis (2 papers, 2024 to 2026). A rare lung disorder characterized by the filling of the pulmonary alveoli with proteinaceous material which stains positive with periodic acid-Schiff stain. "These include genes associated with pulmonary alveolar proteinosis (MARS1, CSF2RA, CSF2RB, OAS1 and GATA2), autoinflammatory disorders (STING1 and COPA) and other complex syndromes (TBX4, FARSA, FARSB and FLNA)." (PMID 41041870, 2026). "Similarly, pulmonary disease is pronounced in individuals with bi-allelic FARSB25,26,32 and MARS1 variants, including a MARS1-specific form of pulmonary alveolar proteinosis." (PMID 38956874, 2024).
pulmonary disease (2 papers, 2024 to 2025). "Methionine supplementation in over 10 patients with MARS1 deficiency has yielded consistent clinical benefit, including resolution of pulmonary disease, improved growth and feeding, and prevention of recurrence posttransplant." (PMID 41404429, 2025).
autoimmune pancreatitis (1 paper, 2025). "The specimen was designated as negative by CCM in one patient, in whom the final clinicopathologic diagnosis was autoimmune pancreatitis and MARS1 staining was negative." (PMID 40722532, 2025).
Cognitive impairment (1 paper, 2021). Abnormal cognition is characterized by deficits in thinking, reasoning, or remembering. "Mutations in MARS1 cause AR HSP complicated by cognitive impairment and nephrotic syndrome, as well as AD Charcot-Marie-Tooth Disease type 2 U." (PMID 33646413, 2021).
Coronary artery atherosclerosis (1 paper, 2025). "Coronary artery atherosclerosis (LAD-lesion area) was positively correlated with WDR62 and MARS1 transcript levels, and negatively correlated with FGGY, PAQR8, and RPS20 transcript levels (p < 0.05)." (PMID 40709334, 2025).
hyperhomocysteinemia (1 paper, 2025). A serious metabolic condition caused by mutations in the MTHFR gene, medications, or nutritional deficiency. "Competitive inhibition of MARS1 with N-acetylcysteine (NAC) attenuates endothelial senescence and improves erectile function in middle-aged individuals with hyperhomocysteinemia by reducing HTL, rather than Hcy itself, while synergizing with tadalafil." (PMID 41281764, 2025).
lymph node metastasis (1 paper, 2023). "In a multivariate analysis, lymph node metastasis and high MARS1 expression were associated with a poor prognosis of PDAC." (PMID 38001673, 2023).
microtia (1 paper, 2024). "Studies have highlighted the association between MARS1 mutations and microtia, providing insights into the genetic mechanisms underlying this condition." (PMID 38594752, 2024). "In this study, missense variants in the MARS1 gene have been identified in individuals with microtia." (PMID 38594752, 2024). "In the non-syndromic microtia group, the most frequently found gene was GSC exon 2 (25%; 6) and FANCB (16.67%); HOXA2, GSC exon 3, MARS1, CDT1 were found respectively in two (8.33%) cases." (PMID 38594752, 2024). "Based on our findings, 64 cases (72.72%) were syndromic microtia [TCOF1 (43.75%), SIX2 (4.69%), and HSPA9 (4.69%)] and 24 cases (27.27%) were non-syndromic microtia [GSC exon 2 (25%), FANCB (16.67%), HOXA2 (8.33%), GSC exon 3 (8.33%), MARS1 (8.33%), CDT1 (8.33%)]." (PMID 38594752, 2024). "In addition, HSPA9, MARS1, and TCOF1 were the only genes related to familial microtia." (PMID 38594752, 2024). "In the syndromic microtia group, the most common genes were TCOF1 (43.75%), SIX2 (4.69%), and HSPA9 (4.69%), while in the non-syndromic microtia group, the most frequently found gene was GSC exon 2 (25%), FANCB (16.67%), HOXA2 (8.33%), GSC exon 3 (8.33%), MARS1 (8.33%), and CDT1 (8.33%)." (PMID 38594752, 2024).
pancreatic ductal adenocarcinoma (1 paper, 2025). An infiltrating adenocarcinoma that arises from the epithelial cells of the pancreas. "In our study, we observed pronounced MARS1 expression in pancreatic ductal adenocarcinoma (PDAC), suggesting its utility as a diagnostic indicator." (PMID 40722532, 2025). "In pancreatic ductal adenocarcinoma (PDAC), elevated MARS1 expression correlates with poor prognosis, and in our previous study, it was identified—alongside lymph node metastasis—as an independent predictor of unfavorable outcomes in PDAC patients." (PMID 40722532, 2025).
renal carcinoma (1 paper, 2025). A carcinoma arising from the epithelium of the renal parenchyma or the renal pelvis. "For example, MARS1 was a significant risk factor in at least 10 cancers, whereas LCMT1 and LCMT2 were protective in several tumors, especially renal cancers." (PMID 41441975, 2025).
round cell liposarcoma (1 paper, 2022). A poorly differentiated liposarcoma, characterized by the presence of solid sheets of primitive round mesenchymal cells and the absence of myxoid stroma. "Because the MARS1 mRNA would also be stabilized by the TLS-CHOP mRNA through the same mechanism, it would be interesting to determine whether the clinical significance of the TLS-CHOP fusion with regard to cancer relates to stabilization of the MARS1 transcript in myxoid and round cell liposarcomas." (PMID 35501376, 2022).
stricture (1 paper, 2025). "We previously reported that the high sensitivity and accuracy of MARS1 IF staining in brush cytology specimens enabled detection of biliary malignancy in indeterminate biliary strictures." (PMID 40722532, 2025).
trichothiodystrophy (1 paper, 2022). Trichothiodystrophy or TTD is a heterogeneous group disorders characterized by short, brittle hair with low-sulphur content (due to an abnormal synthesis of the sulfur containing keratins). "Pathogenic mutations in MARS1 can cause trichothiodystrophy, a rare hereditary neurodevelopmental disorder characterized by sulfur-deficient brittle hair, nails, and scaly skin." (PMID 36158645, 2022).
cancer (9 papers, 2017 to 2025). A tumor composed of atypical neoplastic, often pleomorphic cells that invade other tissues. "Molecular assessment using MARS1 as cancer-specific marker significantly improved the diagnostic performance of brushing cytology because MARS1 IF staining differentiated the atypical cells observed in Pap staining." (PMID 40722532, 2025). "Considering that UV irradiation is a carcinogenic stimulus and AIMP3 is a tumor suppressor maintaining genomic stability, dysregulated phosphorylation of MARS1 at S662 may be associated with cancer development." (PMID 35501376, 2022). "MARS1 is highly expressed in multiple cancer types and is increasingly recognized for its role in tumorigenesis and cancer progression." (PMID 40722532, 2025). "EPRS1, methionyl-tRNA synthetase 1 and lysyl-tRNA synthetase 1 also play essential roles in the progression and metastasis of cancer cells by regulating different signals." (PMID 36675119, 2023). "We evaluated the ability of the expression level of methionyl-tRNA synthetase 1 (MARS1)-which facilitates cancer growth by modulating protein synthesis and the cell cycle-to predict the prognosis of PDAC." (PMID 38001673, 2023). "High MARS1 expression in carcinoma can be used to diagnose cancer in indeterminate specimens." (PMID 40722532, 2025). "MARS1 and RARS1 are also associated with unfavorable outcomes in at least three different cancer types (ACC, KIRC, LGG, and MESO for MARS1; HNSC, LIHC, and LUAD for RARS1)." (PMID 33266490, 2020). "Notably, 40 DERIs were found to be specifically detected in the nuclear fraction, and many of these were from known cancer‐related genes, including AGRN, DKC1, PKMYT1, PLK1, and MARS1." (PMID 36461702, 2023). "The effect of MARS1-mediated CDK4 stabilization is more prominent in p16INK4a-negative cancers because MARS1 and p16INK4a appear to compete for interaction with CDK4." (PMID 35501376, 2022). "Indeed, p16INK4a-negative cancer cell lines show a higher positive correlation for MARS1 and CDK4 protein levels than p16INK4a-positive cancer cell lines." (PMID 35501376, 2022).
tumor (3 papers, 2020 to 2025). "Multi-omics analyses revealed consistently elevated expression of AHCY, BUD23, LCMT1, MARS1, METTL6, SCLY and SEPHS1 in various tumor types." (PMID 41441975, 2025). "Specifically looking at the cytoplasmic aaRS members, the genes that are preferentially amplified across most tumor types are TARS1, GARS1, MARS1, AIMP2, and AIMP3/EEF1E1." (PMID 33266490, 2020).
autosomal recessive disease (1 paper, 2026). Autosomal recessive form of disease. "Firstly, the present study was based on molecular investigations of index cases, and for autosomal recessive diseases (e.g., ABCA3, MARS1, CSF2RB), most often concerned the first affected individual in the family." (PMID 41041870, 2026).
neurodegenerative disease (1 paper, 2023). A disorder of the central nervous system characterized by gradual and progressive loss of neural tissue and neurologic function. "Thus, MARS1 is a type of tRNA synthase gene, and MARS1 mutations may cause ISR activation to drive neurodegenerative diseases." (PMID 36641423, 2023).
MARS1 also shares sentences with these, for which no sentence is quoted: brucellosis (4 papers); African trypanosomiasis (1); anemia (1); cervical cancer (1); cholestasis (1); colon cancer (1); hepatocellular carcinoma (1); influenza (1); metabolic disease (1); microcephaly (1); nephrotic syndrome (1); neurodevelopmental disorder (1); pancreatic adenocarcinoma (1); peripheral neuropathy (1); renal cell carcinoma (1); trigeminal neuralgia (1).